BRCA1 (BRCA1 DNA repair associated)
Diseases named in the same sentence as BRCA1 in open-access papers (continued):
Sharing a sentence is not in itself a finding about the gene and the disease.
cancer (continued). "The potential application of the NBR2 gene, which shares a bi-directional promoter with the BRCA1 gene, has also been revealed in cancer diagnosis." (PMID 34926299, 2021). "For example, BRCAPRO, available in the BayesMendel R package, considers two cancers (breast and ovarian) and two genes (BRCA1 and BRCA2)." (PMID 34406119, 2021). "Main targets for PARPi therapy are BRCA1/2 mutant or HR defective cancer types, but it is also effective in tumors with RAD51C, RAD51D, and PALB2 mutations." (PMID 33498235, 2021). "Our results demonstrate that β-catenin activation acts synergistically with BRCA1 or BRCA2 abrogation to kill cancer cells." (PMID 34389725, 2021). "This study highlights the extent to which BRCA CNVs play an important role in the etiology of cancer in Latin America, and particularly in Mexico where CNVs represented 34.5% of PVs, nearly half of which were the Mexican founder, BRCA1 exon 9–12del." (PMID 34413315, 2021). "BRCA1, a nuclear phosphoprotein, exerts a physiological action in maintaining genomic stability, and it also functions as a cancer suppressor." (PMID 34311656, 2021). "Loss of function mutations in the BRCA1 and BRCA2 genes not only increase the chance of developing cancer, but they also decrease the viability and proliferative capacity of normal cells." (PMID 33670893, 2021). "Considering the distinct molecular roles of BRCA1 and BRCA2, it is understandable that the pathogenic variants of BRCA1 and BRCA2 are associated with different subtypes in cancers." (PMID 35008774, 2021). "Germline mutations in BRCA1 or BRCA2 tumour suppressor genes predispose individuals to breast, ovarian, prostate and other types of cancer." (PMID 34389725, 2021). "HR pathway defects, including BRCA1/2 dysfunction, appear to be present in at least 50% of these cancers, and alterations in the Rb cell cycle regulation pathway, including CCNE1 and RB1 dysfunction, are observed in about 30%." (PMID 33922503, 2021). "Individuals with pathogenic germline BRCA1/BRCA2 alterations have an increased risk of breast, ovarian, pancreatic, prostate, and other cancers." (PMID 33619265, 2021). "OXA also inhibited homologous recombination by CDK1 activity and importantly made cancers with normal BRCA1 function sensitive to PARP inhibition." (PMID 34497808, 2021). "Genetic testing of BRCA1/2 has become the standard of care for all women with HGSC, with the primary goal of identifying hereditary cancer families to provide accurate risk assessment, surveillance, and risk reduction options for at‐risk individuals." (PMID 33030818, 2021). "Similar results have been observed in clinical settings from several cohorts of patients with sporadic and hereditary breast carcinogenesis; specifically, significant overexpression of HIF-1α was reported in BRCA1-related cancers." (PMID 33513753, 2021). "Although PARP inhibitors were found to be selectively active in a subset of tumors harboring BRCA1 or BRCA2 mutations due to the synthetic lethality of PARP inhibition and this particular HRD, it also has a role in BRCA wild type cancers." (PMID 34201502, 2021).
cancer (continued). "Translational research performed in SA involving the highly penetrant BRCA1 and BRCA2 cancer susceptibility genes has identified various recurrent and founder variants as targets for both pharmacogenetic and cascade testing across population groups." (PMID 34660253, 2021). "Cancer cells with defective BRCA1 or BRCA2 tumor suppressor genes cannot perform homologous recombination." (PMID 34070839, 2021). "Next, we applied RT-qPCR to examine the effect of arecoline, the principal alkaloid of ANE, on the expression of ATM and BRCA1 in cancer cells." (PMID 34068585, 2021). "If pathogenic or likely pathogenic alterations in BRCA1, BRCA2, ATM, PALB2, and CHEK2 are found, and/or there is a strong family history of cancer, then patients should be referred for genetic counselling and confirmatory germline testing." (PMID 33630412, 2021). "Nevertheless, RAD51 overexpression has been previously reported in BRCA1/2 mutant cancer cells exhibiting HRD phenotype." (PMID 34762643, 2021). "BRCA1 is a key factor in the DNA double-strand break repair of other genes that induce human cancers." (PMID 31908633, 2020). "In this network, four FA-gene products (FANCD1/J/N/S) are previously well-known DNA damage repair proteins (respectively for BRCA1/2, BRIP1 and PALB2), conferring human cancer susceptibility in breast, ovary, prostate, and/or others." (PMID 33099537, 2020). "Germline heterozygous mutations in BRCA1, BRCA2, and PALB2 were found in eight children with a spectrum of cancers including leukemia, CNS tumors, neuroblastoma, osteosarcoma, and rhabdomyosarcoma." (PMID 32962238, 2020). "Analysis of these genes revealed significant upregulation in APE1, BRCA1, Chk1, Chk2, and TopBP1 for all cancer types." (PMID 32111912, 2020). "The TD Group 1 mutational signature, which is characterized by abundant small (∼10 kb) TDs with microhomology breakpoints, is observed in BRCA1 mutant cancers." (PMID 32182354, 2020). "NUSAP1 has been demonstrated to regulate several cancer-promoting genes and pathways, including BRCA1, Wnt/β-catenin, mTORC1, Hedgehog, etc." (PMID 33489890, 2020). "The identification of BRCA1/2 genetic alterations before cancer development, grant patients the chance to benefit from various medical cancer prevention approaches." (PMID 32778078, 2020). "Oncology specialists who expressed interest in incorporating POC BRCA1/2 genetic testing in their cancer care pathway confirmed that they would screen all SA patients with this assay, regardless of ethnic group or language." (PMID 33643918, 2020). "Common synthetic lethality partnersare BRCA1/2, which play a vital role in annealing RAD51 to ssDNA;however mutations in these proteins are quite common, and when this occurs, the cancer cell can compensateby utilizing RAD52 to perform the task instead." (PMID 33135887, 2020). "Subsets of BRCA1 mutant cancers reported in the TCGA database show increased RNF168 mRNA expression." (PMID 32182354, 2020). "A PARP inhibitor inhibits the action of PARP1 in HBOC-related cancers in which the BRCA1/2 gene is dysfunctional, and specifically leads cancer cells to apoptosis." (PMID 33327492, 2020). "Autophagy and exosome transport are multifaceted processes, and their role in cancer development, progression, and immunity relates to BRCA1/2 expression and genetic stability." (PMID 33409454, 2020). "Breast cancer susceptibility gene (BRCA), including BRCA1 and BRCA2, are involved in the homologous recombination repair of DNA double-strand breaks." (PMID 33054725, 2020). "Pharmacological compounds that disrupt BRCA1 complex formation are developed for use in cancer therapy: Chemosensitivity of cancer cells in response to cisplatin therapy is attenuated by DNA repair." (PMID 33142801, 2020). "These evidences suggest that quantitative methylation analysis of BRCA1 promoter would be needed to predict the clinical behavior of hypermethylated BRCA1 cancer." (PMID 32269964, 2020).
cancer (continued). "The mutational signature for BRCA1/BRCA2 mutations, or Signature 3, was reconfirmed in this study, and documented in version 2 of the Catalog of Somatic Mutations in Cancer (COSMIC) mutational signatures." (PMID 32269964, 2020). "BRCA1/2 heterozygotes were more than twice as likely to have a family history of cancer (12/21, 57.1%) than wild-types (134/534, 25.1%)." (PMID 32300229, 2020). "Many studies suggest that the status of the DDR pathway affects cancer cells’ response to chemotherapy, with loss of DDR elements increasing the sensitivity to DNA-damaging platinum and PARP inhibition, such as BRCA1, BRCA2, BARD1, ATM, and PALB227." (PMID 32457312, 2020). "Several cancer-derived mutations have been reported in the C-terminal region of BARD1, and this region is required for BRCA1/BARD1-mediated inhibition of MT aster formation." (PMID 32722046, 2020). "Collectively our results are encouraging that Olap + Chk1i shows synergistic activity towards both BRCA1 mutant OC cancer cells which either olaparib naïve or olaparib resistant." (PMID 32098452, 2020). "Six pathogenic variants (in BRCA1,BMPR1A,FANCA,FANCC,NBN genes) with cancer related phenotype and three unsolicited variants (in BRCA2,PALB2,RAD50 genes) were reported to patients." (PMID 31937788, 2020). "Our results show that the mutation frequency was 4.1% in BRCA1 and BRCA2 and 5.4% in other cancer genes." (PMID 31963545, 2020). "BRCA1/2-associated FCH was observed in 135 (28.54%) patients with PC (68, 14.38%), breast (44, 9.30%), pancreatic (31, 6.55%), or ovarian (8, 1.69%) cancers." (PMID 33351846, 2020). "Subsequent studies have revealed that loss of proteins associated with 53BP1, such as PTIP, RIF1, DYNLL1, and the Shielding complex, can also rescue the HR repair defect and PARPi sensitivity of human BRCA1 mutant cancer cells." (PMID 32257107, 2020). "DAVID–KEGG pathway analysis of genes in the amplified region of TM00091 revealed that the pathways in cancer, the PI3K–AKT signaling pathway, the MAPK signaling pathway, etc. were involved in this BRCA1-deficient tumor." (PMID 32978388, 2020). "The Alu retroelements are fragments of approximately 300 nucleotides that are reported as being inserted in many genes such as BRCA1 and BRCA2 and are related to an increased cancer risk." (PMID 32039725, 2020). "The BRCA1 protein acts as a tumor suppressor which prevents cancer cells from growing in an uncontrolled way." (PMID 33330383, 2020). "On the other hand, cancer with homologous BRCA1 hypermethylation showed a good response to an emerging therapeutic agent (described in a later section), the PARP inhibitor, which was same as the response of cancer with BRCA germline mutation." (PMID 32269964, 2020). "The use of NQO1-bioactivatable drug (e.g., β-lap) with PARP inhibitors have been shown to significantly expand the clinical application of PARP inhibitors outside of BRCA1/2 mutant cancers for which the majority of PARP inhibitors are currently approved." (PMID 32295316, 2020). "Thismakes RAD52 an appealing target for cancer therapy, as it will onlyhave key function in HR when BRCA1/2 are inactive: this will thereforehave a selective effect on cancer cells, without influencing healthcells." (PMID 33135887, 2020). "Studies showed that KDM5B is upregulated in certain cancers and plays roles in the transcriptional repression of tumor suppressor genes, such as BRCA1." (PMID 32093041, 2020). "While BRCA1 is the most recognized predisposing gene for BC and OC, RAD51C was first identified as a putative cancer-predisposing gene in BC/OC families in 2010." (PMID 32276467, 2020). "For others, the decision around breast risk-reducing surgery was linked to a sense of self and a sense of “being a woman” [P3/ 52yrs/BRCA1/cancer]." (PMID 32812179, 2020). "We performed a detection of BRCA1/2 exons in a total of 7580 cases and 4874 controls spanning four cancers." (PMID 32879886, 2020).
cancer (continued). "We aimed to clarify the relationship between BRCA1/2-associated FCH and PC, and to assess its relationship with cancer aggressiveness." (PMID 33351846, 2020). "Germline mutations in BRCA1 and BRCA2 are associated with an increased risk of developing several types of cancer, including breast, prostate, and ovarian cancer." (PMID 32545454, 2020). "Epigenetic silencing of DNA repair genes such as MLH1, MGMT, BRCA1, FANCF, CHFR and SLFN11 can lead to gene mutations and genomic instability in cancer cells." (PMID 32974031, 2020). "Strengths of this study include the large cohort sample sizes of BRCA1/2 carriers and use of independent prospective cohort data to validate PRS associations with cancer risks." (PMID 32665703, 2020). "It has been reported in 90% (breast) and 91% (ovarian) of BRCA1-associated cancers and in 54% (breast) and 84% (ovarian) of BRCA2-associated cancers." (PMID 32481735, 2020). "Our observation is in line with a study that measured a total of 20% of BRCA1 or BRCA2 deleterious germline mutations on forty Algerian primary invasive unrelated BC cases who attended the Anti-Cancer Center of Setif." (PMID 32102524, 2020). "Being the most important predisposing genes in female malignancies, BRCA1 and BRCA2 were among the first cancer genes undergoing full sequencing analysis starting from 1996." (PMID 32127026, 2020). "Cancers in women with BRCA1 and BRCA2 PVs were smaller overall with 75.0% and 85.4% being ≤20 mm, respectively, reflecting the benefits of MRI screening." (PMID 33317064, 2020). "BRCA1 and BRCA2 are the genes most often found mutated and increase the risk for early age onset BC and/or OC, and often after a first cancer a second cancer is common." (PMID 32211400, 2020). "For example, ORs for known BC and OC predisposing genes such as BRCA1 and BRCA2 are high, and variants in these genes have been shown to confer high risk to cancer in carriers." (PMID 32726901, 2020). "A deletion in the linker between the UIM domains of RAP80 (ΔE81) found in cancer patients disrupts ubiquitin binding, preventing BRCA1 sequestration to DNA repair foci." (PMID 33142801, 2020). "Establishing the interaction between BMPR2 and BRCA1 strengthened the link between cancer and PAH; however, the findings need to be corroborated with a larger dataset." (PMID 33086628, 2020). "DDR and related genes were found frequently methylated in human cancers, including BRCA1/2, MGMT, WRN, MLH1, CHFR, P16 and APC." (PMID 32974031, 2020). "Mutations in the BRCA1 or BRCA2 genes result in a defect in HR repair, which causes cancer cells with these mutations to become “addicted” to error-prone alt-EJ pathways for their survival." (PMID 32660124, 2020). "Even in the setting of inherited germline mutated BRCA1 or BRCA2, which is present in all the cells of the breast, only solitary cancers or multifocal cancers limited to 2 or 3 foci at most arise." (PMID 33196707, 2020). "We presented three benchmarks of Belgian laboratories performing targeted NGS in routine cancer treatment on solid tumors, hematologic malignancies, and BRCA1/2 genes, which took place between 2017 and 2018." (PMID 33138022, 2020). "The aim of this study was to compare patient-reported outcomes (PROs) of BRCA1/2 mutation carriers, either after bilateral prophylactic mastectomy (BPM) or during breast surveillance, to improve shared decision-making in their cancer risk management." (PMID 31832891, 2020). "Until then, carriers of mutations in the genes BRCA1 and BRCA2 as well as in other less frequent cancer genes should be taken care of under trial conditions." (PMID 32140806, 2020).
cancer (continued). "Among these, RAD51C was found constitutively hypermethylated in sporadic BC, as showed by Hansmann and colleagues, who identified hypermethylation at both BRCA1 and RAD51C promoters in 1.4% and 0.5% of high-risk cancer patients, respectively." (PMID 32276467, 2020). "The third most frequent PV, observed in 14 families and involving a total of 38 subjects (8%), including 15 cancer patients (14 probands and 1 family member), is named BRCA1-633delC (HGVS nomenclature: c.514del; p.Gln172fs)." (PMID 32380732, 2020). "By using liquid biopsy or circulating cell-free DNA (cfDNA), lots of BRCA reversion mutations have been discovered to restore the open reading frame (ORF) of BRCA1/2 and confer resistance to PARPi-based therapy in various cancers." (PMID 32563252, 2020). "We focused on ADAT2, CCNL2, DBF4B, and TRIM45 mRNAs that played key roles in cancer biology to demonstrate that alteration of their translational efficiency occurred via a BRCA1-dependent mechanism in cultured cells and in patient tumors." (PMID 32290274, 2020). "For example, germline mutations in BRCA1 and BRCA2 predispose to multiple cancer types, specifically to ovarian and breast cancer in women and prostate cancer in men." (PMID 32239503, 2020). "As the molecular functions of BRCA1 and BRCA2 have been elucidated, the clinical focus on these cancer predisposition genes shifts toward the development of therapeutic strategies." (PMID 32269964, 2020). "Since 2018, patients relapsing after previous chemotherapy in the neoadjuvant, adjuvant, or metastatic setting are eligible to treatment with PARP inhibitors such as olaparib and talazoparib, inducing synthetic lethality in BRCA1 or BRCA2 cancers." (PMID 32053991, 2020). "BRCA1 has proposed functions as a transcription factor controlling differentiation in non-transformed cells, but a primary role in DNA repair in cancer." (PMID 32527287, 2020). "This and previous studies have demonstrated that cancer risks for BRCA1/2 carriers increase with an increasing number of affected first- or second-degree relatives, suggesting genetic or other familial factors modify cancer risks for BRCA1/2 carriers." (PMID 32665703, 2020). "The cancer suppressor gene BRCA1 was highly expressed in GRA16 cells compared with that in control and vector cells (p < 0.05)." (PMID 32927892, 2020). "Decreasing proportion of mutation carriers in other family cancer history categories (41.0% in HBOC and 29.4% in multiple cancer) was dominantly caused by decreasing BRCA1 mutation prevalence." (PMID 32295079, 2020). "The first FDA-approved, DDR-targeted cancer therapeutic drug is olaparib, an inhibitor of poly (ADP-ribose) polymerases (PARP) for the treatment of cancers with inherited BRCA1 or 2 mutations by inducing the synthetic lethality." (PMID 32180730, 2020). "BRCA1 and BRCA2 mutations are relatively frequent in patients who have a family history of cancer, i.e., hereditary breast and ovarian cancer." (PMID 32098267, 2020). "Understanding the underlying mechanisms is critically important for further understanding the interplay among the epigenetics of BRCA1, DNA damage, and repair and its role in the etiology of cancer and neurodegenerative diseases such as AD." (PMID 31963223, 2020). "Cancers occurring among BRCA1 carriers are more frequently classified as medullary, whereas histological subtypes among BRCA2 carriers tend to be more heterogeneous." (PMID 33302444, 2020).